LINC00452 (long independently transcribed non-coding RNA 452)
Synonyms: LINC00453
Gene: Long non-coding RNA gene on chromosome 13 (113,895,103 to 113,921,317, forward strand). Ensembl gene ENSG00000229373.
Diseases named in the same sentence as LINC00452 in open-access papers:
LINC00452 is named in the same sentence as 6 diseases in open-access papers, as found by Europe PMC text mining. Sharing a sentence is not in itself a finding about the gene and the disease. The quoted sentences say what the papers report.
ovarian carcinoma (3 papers, 2020 to 2022). A malignant neoplasm originating from the surface ovarian epithelium. "Aberrant expression of LINC00452 negatively correlates with recurrence-free survival time in ovarian cancer patients." (PMID 34906173, 2021). "Cellular expression and localization of LINC00452 in ovarian cancer cells were detected by qPCR and FISH." (PMID 33168781, 2020). "LINC00452 was found to be upregulated in ovarian cancer cells as well as tumor tissues, and LINC00452 could enhance the carcinogenic characteristics such as cell proliferation, migration, and invasion in vitro, and the growth of xenograft tumor in vivo." (PMID 36233294, 2022). "In vitro, LINC00452 was elevated in all general ovarian cancer cell lines including the serous ovary cancer cells lines OVCAR3, SKOV3 and CaOV3, as well as the ovary epithelial cancer cell lines A2780 and HO-8910 in comparison to the normal ovarian epithelial cell IOSE80." (PMID 33168781, 2020). "We then confirmed by qPCR that LINC00452 was also significantly upregulated in all general ovarian cancer cell lines including OVCAR3, SKOV3, CaOV3, A2780 and HO-8910 cells in comparison to the normal ovarian epithelial cells IOSE80 with the highest abundance detected in CaOV3 cells." (PMID 33168781, 2020). "Our study makes LINC00452 a potential therapeutic target for ovarian cancer." (PMID 33168781, 2020). "To test whether there was LINC00452-related post-translational regulation of ROCK1 in ovarian cancer, we first conducted an in-silico prediction through catRAPID the probability of any physical interaction between LINC00452 and ROCK1 protein." (PMID 33168781, 2020). "So far, our results had suggested that LINC00452 acts as a miR-501-3p sponge controlling ROCK1 expression and subsequently the outcome of RFS in ovarian cancer patients." (PMID 33168781, 2020).
thymoma (1 paper, 2022). A neoplasm arising from the epithelial cells of the thymus. "The results of Pearson correlation analysis showed that only LINC00452 was significantly and positively correlated with CHST4 (r = 0.49, p = 8.953 × 10−3) in the thymoma of patients with TAMG." (PMID 35432149, 2022).
tumor (2 papers, 2020 to 2022). "Overexpression of LINC00452 potentiated CaOV3 cell viability, migration and invasion in vitro as well as xenograft tumor growth in vivo." (PMID 33168781, 2020). "However, simultaneous suppression of ROCK1 dramatically slowed down the tumor growth rate despite of LINC00452 overexpression." (PMID 33168781, 2020).
LINC00452 also shares sentences with these, for which no sentence is quoted: cancer (1 paper); ovarian tumor (1); ovary epithelial cancer (1).